RN7SL623P (RNA, 7SL, cytoplasmic 623, pseudogene)
Gene: Miscellaneous RNA gene on chromosome 5 (170,866,835 to 170,867,144, forward strand). Ensembl gene ENSG00000244501.
Homologues: Orthologues: chimpanzee Metazoa_SRP (99% identical), macaque Metazoa_SRP (94% identical). Paralogues in human: RN7SL45P (78% identical), RN7SL2 (77% identical), RN7SL1 (77% identical), RN7SL220P (76% identical), RN7SL3 (76% identical), RN7SL126P (76% identical), RN7SL732P (75% identical), RN7SL769P (75% identical), RN7SL113P (75% identical), RN7SL559P (75% identical), RN7SL577P (75% identical), RN7SL748P (75% identical), and 697 more.